TBX2 (T-box transcription factor 2)
Diseases named in the same sentence as TBX2 in open-access papers (continued):
Sharing a sentence is not in itself a finding about the gene and the disease.
sarcoma (5 papers, 2018 to 2025). A usually aggressive malignant neoplasm of the soft tissue or bone. "The authors suggested that in sarcomas, TBX2 promoted cell proliferation, and inhibition of its expression led to the repression of tumour growth." (PMID 29659518, 2018). "In humans, it was confirmed that TBX2 is responsible for developing tissue sarcomas in which this gene is overexpressed." (PMID 29659518, 2018). "E-cadherin overexpression in sarcomas reduces anchorage-independent growth and spheroid formation of sarcoma cells through downregulation of phosphorylated CREB1 (p-CREB) and the transcription factor, TBX2, thus inhibiting sarcoma aggressiveness by preventing anchorage-independent growth." (PMID 33076339, 2020). "Our data showed that TBX3 represses TBX2 in RMS cell lines so we asked if this expression correlation could also be observed in additional sarcomas using available patient data." (PMID 30979887, 2019). "In this regard, the transcription factors TBX2 and TBX3 are of particular interest because their overexpression in several carcinomas and sarcomas was shown to enhance cell proliferation, bypass senescence and apoptosis, and promote tumour formation, angiogenesis and metastasis." (PMID 39403898, 2024).
bladder cancer (4 papers, 2017 to 2021). "For instance, methylation of TBX2 and TBX3 were shown to be associated with prognosis and predict progression in bladder cancer." (PMID 30866410, 2019). "An association of methylation of TBX2 and SPRY2 with disease progression has also been demonstrated in bladder cancer and B-cell diffuse lymphoma, respectively, but so far, no studies have been reported in CLL." (PMID 28572861, 2017).
chromosome 22q11.2 deletion syndrome (3 papers, 2013 to 2020). "Interestingly, craniofacial abnormalities reminiscent of the Tbx1-linked DiGeorge’s syndrome have been observed in patients with a microdeletion at 17q21-22, leading to TBX2-haploinsufficiency." (PMID 24130849, 2013). "tbx-2(bx59) mutates a conserved histidine residue within the dimerization domain of the T-box to a tyrosine (H145Y; accession CCD69847), and mutations affecting this domain in human TBX1 result in gain-of-function associated with some cases of DiGeorge and velocardiofacial syndromes." (PMID 23595631, 2013).
gastric cancer (3 papers, 2020 to 2025). A primary or metastatic malignant neoplasm involving the stomach. "Consistent with this, TBX2 up-regulation is associated with drug resistance and the induction of polyploidy in mouse hepatocellular carcinoma and human gastric cancer cells treated with a combination of cisplatin and paclitaxel or cisplatin, paclitaxel and docetaxel." (PMID 39912718, 2025). "It is worth noting that in gastric cancer, the overexpression of TBX2 also led to the up-regulation of MMP-2 and -9 and, while undefined, this may be occurring through TBX2 activation of WNT3A." (PMID 39912718, 2025). "In addition, high TBX2 expression may use to define a subgroup of stage II/III gastric cancer patients who will be more likely to benefit from 5-FU-based PAC." (PMID 32231721, 2020). "However, the roles of TBX2 in gastric cancer (GC) remain unclear." (PMID 32231721, 2020). "Similarly, TBX2 expression was significantly up-regulated in platinum-resistant ovarian cancer patients, cisplatin-resistant endometrial cancer patients and in poor responders to postoperative adjuvant chemotherapy in stage II/III gastric cancer." (PMID 39912718, 2025).
lung adenocarcinoma (3 papers, 2020 to 2024). A carcinoma that arises from the lung and is characterized by the presence of malignant glandular epithelial cells. "The resulting 245 differentially methylated regions were enriched for lung adenocarcinoma-specific 5-mC patterns in TCGA data and indicated transcriptional repression of several genes described to be silenced in NSCLC (e.g., PCDH10, TBX2, CDO1, and HOXA9)." (PMID 36461127, 2022). "TBX2 has statistically high expression levels in patients that were found positive for metastasis to bone marrow compared to patients that did not exhibit this type of metastasis in lung adenocarcinoma (GSE10799)." (PMID 31897234, 2020).
nasopharyngeal carcinoma (3 papers, 2017 to 2025). A carcinoma arising from the nasopharyngeal epithelium. "In nasopharyngeal cancer cells, TBX2 levels inversely correlated with the tumour suppressors PTEN, p21Cip1, p27Kip1 and E-cadherin, and knocking down TBX2 led to their up-regulation and a significant inhibition of proliferation and invasion." (PMID 39912718, 2025).
Obesity (3 papers, 2017 to 2022). Accumulation of substantial excess body fat. "Consistent with the functional enrichment analyses, we identified hub genes related to blood vessel morphogenesis in the darkred module: TBXA2R, FZD4, COL15A1, and TBX2 were positively associated with maternal BMI and/or obesity and with birth weight." (PMID 31110514, 2019).
arterial hypertension (2 papers, 2021 to 2023). "We found that DNA methylations in the promoters of PRDM6, HDAC9, IGFBP3, SYT7, TBX2 and C17orf82 were significantly associated with BP or hypertension in the Chinese Han population." (PMID 35087571, 2021). "In summary, the present study showed that DNA methylation in the promoters of PRDM6, HDAC9, IGFBP3, LRRC10B, SYT7, PDE3A, TBX2 and C17orf82 genes were significantly associated with BP or hypertension." (PMID 35087571, 2021).
congenital heart disease (2 papers, 2015 to 2019). A heart disease that is present at birth. "In this study, we aimed to determine the relationship between common genetic variants in the promoter region of TBX2 gene and the risk of congenital heart disease (CHD)." (PMID 30525309, 2019). "A patient with two copies of TBX2, caused by the chromosome 17q23.2 duplication, was reported to suffer from complex congenital heart defects." (PMID 30525309, 2019). "TBX5 is primarily linked to congenital heart disease; however, the homologs TBX2 and TBX3, which share DNA binding consensus with TBX5, are associated with cancer and invasive cellular behavior." (PMID 26549256, 2015). "In accordance with the previous studies, both duplications and microdeletions of the chromosome fragments containing TBX2 (located at chromosome 17q23) could result in syndromic disorders including heart defects." (PMID 30525309, 2019).
ovarian serous carcinoma (2 papers, 2020 to 2025). "High TBX2 expression was found to be associated with platinum-resistance of ovarian serous carcinoma." (PMID 32647070, 2020).
ventricular septal defect (2 papers, 2018 to 2019). The presence of a defect (opening) in the septum that separates the two ventricles of the heart. "Four novel rare variants in TBX2 promoter region were identified in patients diagnosed with ventricular septal defects." (PMID 30525309, 2019). "In contrast, four novel rare mutations in TBX2 promoter region were indicated to cause ventricular septal defects, indicating the contribution of TBX2 regulatory variants to the occurrence of CHD." (PMID 30525309, 2019).
adrenocortical carcinoma (1 paper, 2025). "Moreover, in adrenocortical carcinoma cells, TBX2 expression promoted resistance to the first-line treatment, doxorubicin, by modulating caspase expression and thus inhibiting apoptosis." (PMID 39912718, 2025). "Indeed, in adrenocortical carcinoma, the PI3K/AKT pathway led to an increase in TBX2 mRNA and protein levels, which consequently promoted anchorage-independent growth." (PMID 39912718, 2025).
atherosclerosis (1 paper, 2021). A disease characterized by the build-up of fatty material and calcium deposition in the arterial wall resulting in partial or complete occlusion of the arterial lumen.
chronic kidney disease (1 paper, 2021). Impairment of the renal function secondary to chronic kidney damage persisting for three or more months. "TBX2 variants were associated with kidney function and chronic kidney disease." (PMID 35087571, 2021).
chronic periodontitis (1 paper, 2024). A chronic inflammatory process that affects the tissues that surround and support the teeth. "In the current investigation, the average concentrations of PGE2 and TBX2 in the GCF were observed to be significantly lower in the control group compared to those with chronic periodontitis." (PMID 39502985, 2024).
cleft palate (1 paper, 2010). Cleft palate is a fissure type embryopathy that affects the soft and hard palate to varying degrees. "Mutations in the frequently deleted gene TBX22 are linked to non-syndromic cleft palate, but TBX2 has no known role in tumorigenesis." (PMID 20126641, 2010).
coloboma (1 paper, 2018). An abnormality in which a part of a structure in one or both eyes is missing. "Using this dataset, we interrogated the superior coloboma patient exome data, and identified a variant in TBX2 (p.Pro329His)." (PMID 29522511, 2018). "Exome sequencing of superior coloboma patients identified rare variants in a Bone Morphogenetic Protein (Bmp) receptor (BMPR1A) and T-box transcription factor (TBX2)." (PMID 29522511, 2018).
deafness (1 paper, 2022). An inherited or acquired condition characterized by the complete loss of the ability to hear from one or both ears. "Thus, Tbx2 is essential for IHC development and co-upregulation of Tbx2 with Atoh1 in supporting cells represents a new approach for treating deafness related to IHC degeneration." (PMID 36687561, 2022).
ductal carcinoma in situ (1 paper, 2026).
empty sella syndrome (1 paper, 2022). Empty sella syndrome (ESS) is a condition that involves the sella turcica, a bony structure at the base of the brain that protects the pituitary gland. "In conclusion, we report a novel skeletal dysplasia with rheumatoid arthritis-like joint degeneration and an empty sella associating with a pathogenic TBX2 variant." (PMID 35311234, 2022).
endometrial cancer (1 paper, 2024). Primary or metastatic malignant neoplasm involving the endometrium (mucous membrane that lines the endometrial cavity). "In endometrial cancer, the mechanism by which PSCA expression occurs is not known, but it is suggested that T-Box Transcription Factor 2 (TBX2), one of the markers involved in endometrial cancer, may play a role in up-regulating PSCA expression." (PMID 38627732, 2024).
endometriosis (1 paper, 2024). The growth of functional endometrial tissue in anatomic sites outside the uterine body. "There were 12 molecules that returned no search results on PubMed, including the transcription regulators IRF2BP2, TBX2 and ZBTB10, suggesting that these endogenous molecules could have as yet unidentified roles in the establishment of endometriosis lesions." (PMID 39385609, 2024).
Hearing impairment (1 paper, 2021). A decreased magnitude of the sensory perception of sound. "Five of the variants that have rare genotypes with large effects are at loci that have not been reported for any type of hearing impairment: FBF1, FSCN2, C10orf90, SH2D4B, and TBX2." (PMID 34108613, 2021).
Inguinal hernia (1 paper, 2019). Protrusion of the contents of the abdominal cavity through the inguinal canal. "Genetic studies from China revealed that DNA sequence variants (DSVs) might contribute to inguinal hernia development by changing the transcriptional activities of TBX1, TBX2, TBX3, Sirtuin 1, and GATA transcription factor 6 (GATA6) gene promoters." (PMID 31024927, 2019).
invasive breast carcinoma (1 paper, 2012). A carcinoma that infiltrates the breast parenchyma. "Interestingly, we found that TBX2 is induced by the EMT-promoting cytokine TGFß, which is often excessively produced by invasive breast cancer cells and has been associated with metastatic tumor progression." (PMID 22844464, 2012).
ischemic stroke (1 paper, 2022). A stroke disorder caused by obstruction of blood flow to the brain, due to thrombotic (local blood clot formation) or embolic (due to a blood clot or other material traveling from another site) event. "Higher methylation levels of 18 targets in AMH, C17orf82, HDAC9, IGFBP3, LRRC10B, PDE3A, PRDM6, SYT7 and TBX2 genes were associated with a lower risk of ischemic stroke." (PMID 35345488, 2022). "According to the results from stage one and stage two, we confirmed that higher methylation levels of 17 targets in AMH, C17orf82, HDAC9, IGFBP3, LRRC10B, PDE3A, PRDM6, SYT7 and TBX2 genes were associated with a lower risk of ischemic stroke." (PMID 35345488, 2022). "Methylation of AMH, C17orf82, HDAC9, IGFBP3, LRRC10B, PDE3A, PRDM6, SYT7 and TBX2 was significantly associated with ischemic stroke." (PMID 35345488, 2022). "The results showed that the mean methylation levels of AMH, C17orf82, HDAC9, IGFBP3, LRRC10B, PDE3A, PRDM6, SYT7 and TBX2 were significantly (Wilcoxon's two sample test) lower in ischemic stroke cases than in controls." (PMID 35345488, 2022).
keloid (1 paper, 2022). An irregularly shaped, elevated mark on the skin caused by deposits of excessive amounts of collagen during wound healing. "In terms of expression level, BMP4, MSX1, TBX2, SIX1, DLX5, and DLX2 were lowly expressed, while HAND2, IRX1, EDN1, and MEF2C were highly expressed in keloid fibroblasts." (PMID 35047146, 2022).
lung hypoplasia (1 paper, 2013). "Reduced size of Tbx2-deficient lungs could therefore relate to increased apoptosis and/or to decreased proliferation of distal epithelial and mesenchymal tissue compartments as shown for other models of lung hypoplasia." (PMID 23341776, 2013).
lung squamous cell carcinoma (1 paper, 2024). "Then we used Human Protein Atlas to determine the expression of TBX2, TBX3, TBX4 and TBX5 in lung squamous cell carcinoma tissues." (PMID 38413457, 2024).
lymph node metastasis (1 paper, 2020). "In this study, we showed that high TBX2 expression was positively associated with lymphovascular invasion, lymph node metastasis, and an increased risk of poor RFS and OS in GC." (PMID 32231721, 2020). "Higher expression of TBX2 was significantly associated with lymphovascular invasion (p=0.024) and lymph node metastasis (p=0.044)." (PMID 32231721, 2020).
microphthalmia (1 paper, 2014). Congenital or developmental anomaly in which the eyeballs are abnormally small. "Further, mutation of Tbx2 in mice likewise causes microphthalmia." (PMID 24681822, 2014).
osteonecrosis (1 paper, 2024). A none disease characterized by death of bone tissue due to a lack of blood supply. "Additionally, miR-486-5p inhibits adipogenesis in mesenchymal stem cells and prevents steroid-induced osteonecrosis by targeting TBX2 and upregulating p21." (PMID 39200271, 2024).
ovarian carcinoma (1 paper, 2019). A malignant neoplasm originating from the surface ovarian epithelium. "For instance, over-expression of TBX2 and TBX3 were reported in breast, bladder, liver and ovarian cancers." (PMID 30866410, 2019).
pulmonary arterial hypertension (1 paper, 2021). Pulmonary arterial hypertension (PAH) is a group of diseases characterized by mean pulmonary artery pressure >20 mmHg and elevated pulmonary arterial resistance leading to right heart failure. "Heterozygous SNVs in TBX4 and CNV deletions involving TBX4 and TBX2 have been reported also in pediatric and adult patients with pulmonary arterial hypertension (PAH), ischiocoxopodopatellar syndrome (MIM# 147891), and developmental delay, heart defects, and limb abnormalities." (PMID 33478486, 2021).
silicosis (1 paper, 2025). Silicosis is a respiratory disease caused by breathing in (inhaling) silica dust. "After nebulization, Tbx2 mRNA‐loaded nanoparticles effectively restore lung function in silicosis mice." (PMID 41211661, 2025). "T‐box transcription factor 2 (Tbx2), a crucial transcription factor in lung development and growth, is down‐regulated in silicosis." (PMID 41211661, 2025).
squamous cell carcinoma (1 paper, 2024). A carcinoma arising from squamous epithelial cells. "Like TBX2, TBX3 has decreased protein expression by 1.5-fold in pulmonary adenocarcinoma, and by onefold in non-squamous cell carcinoma." (PMID 38413457, 2024).
urothelial carcinoma (1 paper, 2015). A malignant neoplasm derived from the transitional epithelium of the urinary tract (urinary bladder, ureter, urethra, or renal pelvis). "Methylation of TBX2 and TBX3 has been found to be associated with urothelial tumor progression, however their full role in urothelial carcinoma is not yet clear." (PMID 26008846, 2015).